CD34 (CD34 molecule)
Diseases named in the same sentence as CD34 in open-access papers (continued):
Sharing a sentence is not in itself a finding about the gene and the disease.
dementia (3 papers, 2024). Loss of intellectual abilities interfering with an individual's social and occupational functions. "The relationship between CD34+CD133+ cell proportion (%) and AD risk or all-cause dementia risk was studied after adjusting for different covariates." (PMID 38854406, 2024). "In contrast to positive associations with some vascular diseases, with an increase in the CD34+CD133+ EPC quartiles, the incident rates of AD (5.85% vs. 3.94% vs. 2.99% vs. 2.09%, P = 0.04) and all-cause dementia (7.66% vs. 5.56% vs. 4.41% vs. 2.86%, P = 0.02) decreased." (PMID 38854406, 2024). "Again, among their counterpart genotype carriers (KIRREL3 rs4144611 GG + TG or rs580382 TT + CT carriers and EXOC6B rs61619102 GG + GC carriers), there were no such relationships between CD34+CD133+ quartiles and AD or all-cause dementia risk." (PMID 38854406, 2024). "Among them, only CD34+CD133+ EPCs, but none of the other cell types, significantly impacted the risk of AD (HR = 0.64, P = 0.02) and all-cause dementia (HR = 0.63, P = 0.006) after adjusting for age, sex, years of education, APOE ε4, and vascular diseases." (PMID 38854406, 2024). "The increase in CD45dim/CD34+/CD133+ following normobaric 100% oxygen exposures holds promise for both CHF and managing the progression of executive function, cognitive decline, Alzheimer’s and dementia, and possibly other diseases that correlate with decreased endothelial function." (PMID 39974348, 2024).
dengue (3 papers, 2014 to 2024). "RAG2-/-γc-/- human CD34+, NSG-A2 and NSG-BLT models are potentially valuable for investigating the mechanisms underlying dengue-induced ADE." (PMID 39312399, 2024). "Additionally, RAG2-/-γc-/- (RAG2 -hu) and RAG2-/-γc-/- human CD34+ have been tested for dengue fever immune pathogenesis and antibody neutralizing activity." (PMID 39312399, 2024). "Interestingly, in contrast to the CD34+ humanized mouse models, the hu-SGM3 PBMCs dengue model showed weight loss, diarrhea, and gastrointestinal bleeding in some animals, indicating that this model can recapitulate some clinical signs of dengue." (PMID 39204240, 2024). "Another dengue animal model has been established by transplanting human CD34+ cells into NON/SCID (nonobese diabetic/severe combined immunodeficient) mice, showing clinical signs resembling human dengue fever disease." (PMID 25157370, 2014).
dermatitis (3 papers, 2015 to 2021). An inflammatory process affecting the skin. "We investigated the number of CD34-positive blood vessels and podoplanin (recognized by the D2–40 antibody)-positive lymphatic vessels in nipple tissue in Paget disease, dermatitis, and healthy tissues." (PMID 32527320, 2020). "We calculated the average CD34-positive BVD and podoplanin (D2–40)-positive lymphatic vessel density (LVD) and the proportion of proliferating of endothelial cells in 14 Paget disease, 3 dermatitis biopsy, and 14 age-matched control cases." (PMID 32527320, 2020).
diffuse large B-cell lymphoma (3 papers, 2020 to 2024). "Optimal mobilization of autologus CD34+ cells for ASCT has been reported to improve overall survival (OS) and event-free survival in peripheral T-cell lymphoma, and higher graft CD34+ cell counts have been associated with better OS in patients with diffuse large B-cell lymphoma." (PMID 39091501, 2024).
ductal carcinomas (3 papers, 2008 to 2019). "A composite phenotype characterized by VEGF positive epithelial cells and SMA positive/CD34 negative stromal cells, is identified mostly in intermediate and high grade in situ ductal carcinomas." (PMID 18384688, 2008).
endotoxemia (3 papers, 2015 to 2024). "To assess the clinical relevance of MOTS-c levels in endotoxemia-induced myocardial coronary injury and heart dysfunction, we examined circulating CD34+ ECs and EPCs isolated from human septic patients." (PMID 38389837, 2024). "With the exception of B. cenocepacia LPS- and B. thailandensis LPS-induced brains, we found that CD34 levels were increased in brains with endotoxemia." (PMID 30206252, 2018). "Similar results were obtained in endotoxemia: the TLR4-positive CD34+ CD38− cells and the fluorescence intensity increased by 63 % and 46 %, respectively." (PMID 26272069, 2015).
fibroepithelial tumors (3 papers, 2008 to 2023). "These may be differentiated from fibroepithelial tumours on the basis that the spindle cells stain negative for CD34." (PMID 18673528, 2008).
hepatic angiosarcoma (3 papers, 2019 to 2025). "Staining against endothelial markers, such as vWF, CD31, or CD34, is commonly used for the diagnosis of human hepatic angiosarcoma." (PMID 31095587, 2019). "Cluster of Differentiation 34 (CD34) and Erythroblast transformation specific regulated gene (ERG) histopathology confirmed hepatic angiosarcoma." (PMID 40541022, 2025). "Furthermore, CD34 marker which was found to be negative in all of the cases in this investigation can be a very useful marker in the diagnosis of hepatic angiosarcoma which frequently stains positive for this marker." (PMID 34162402, 2021).
Histiocytosis (3 papers, 2022 to 2025). An excessive number of histiocytes (tissue macrophages). "We now provide the first evidence of circulating CD34+ progenitors harboring a histiocytosis-associated driver alteration in a patient with isolated cutaneous histiocytosis." (PMID 40453139, 2025). "Xenotransplantation of CD34 + HSPCs from BRAF mutant patients with histiocytosis (ECD or MH) resulted in the development of histiocytosis-like lesions and detection of BRAF V600E in circulating monocytes of ECD and mixed histiocytosis patients." (PMID 39592527, 2024).
hyperplasia (3 papers, 2011 to 2022). An abnormal increase in the number of cells in an organ or a tissue with consequent enlargement. "Statistically increased values of cell proliferation (CD34+ CD61+) were observed in prostate adenocarcinoma and hyperplasia cases reported to non-malignant adjacent cell samples (PCa 28.79 ± 10.14; BPH 40.65 ± 11.88 vs. C 16.15 ± 2.58, p < 0.05)." (PMID 35884977, 2022).
Infertility (3 papers, 2021 to 2024). "No or only negligible expression of hematopoietic and endothelial cell markers (CD14, CD8a, CD15, CD31, CD34, CD45, CD117 and CD133) was detected in MenSCs from healthy volunteers and patients with unexplained infertility." (PMID 34202508, 2021).
injury (3 papers, 2014 to 2019). Damage inflicted on the body as the direct or indirect result of an external force, with or without disruption of structural continuity. "Here we investigated the therapeutic potential of freshly isolated human umbilical cord blood CD34+ progenitor cells (fCB-CD34+ cells) in a mouse model of acute lung injury." (PMID 24558433, 2014). "CD34+ McSCs, and their counterparts in human skin, may be useful for myelinating neurons in vivo, leading to new therapeutic opportunities for demyelinating diseases and traumatic nerve injury." (PMID 31017901, 2019).
intervertebral disc degeneration (3 papers, 2022 to 2024). "Since CD34-positive cells contribute to maintenance of the endothelium and angiogenesis, inadequate angiogenesis related to lower adaptability to hypoxia might increase the risk of height loss via the development of intervertebral disc degeneration." (PMID 37796945, 2023).
lentivirus infection (3 papers, 2010 to 2024). Virus diseases caused by the Lentivirus genus. "We achieved overexpression and repression of the CTDSPL2 gene in CD34+ cells by lentivirus infection." (PMID 20932329, 2010). "To reach this conclusion, we first developed a rapid and efficient fluorescent labelling procedure of human CD34+ cells based on lentivirus infection allowing long term stem cell staining without major alterations of the properties of transduced cells." (PMID 38693109, 2024).
lung disease (3 papers, 2011 to 2025). "In contrast, while the CD45+Pro-Col-Iα1+ cells obtained from obtained from patients with lung disease also expressed high levels of CD14, many of these cells also expressed CD34." (PMID 21586112, 2011). "Furthermore, in spite of the well-known role of CD34+ hematopoietic stem cells in hematopoietic transplantation, their therapeutic role in pulmonary diseases has not been widely studied." (PMID 34746417, 2021).
lymphedema (3 papers, 2023 to 2025). Excess fluid collection in tissues, causing swelling. "The aim of the present study was to report important changes in immunostained CD34 cells following the treatment of lower limb lymphedema using a specific lymphatic therapy technique." (PMID 36975385, 2023). "The treatment of primary lymphedema of the lower limbs resulted in the clinical reversal of fibrosis and an increase in the number of immunomarked CD34 cells." (PMID 36975385, 2023).
mucositis (3 papers, 2022 to 2025). Mucositis is inflammation and damage of the mucous membranes lining the mouth and other parts of the gastrointestinal (GI) tract. "Specifically, KFX significantly reduced the odds of grade 3–4 mucositis (OR = 0.118, 95% CI 0.029–0.488, p = 0.003) and infection (OR = 0.115, 95% CI 0.030–0.439, p = 0.002) after adjusting for age, CD34+ dose, disease stage, and other clinical variables." (PMID 41480530, 2025). "The peri-implantitis group had significantly higher levels of vascular endothelial growth factor (VEGF), CD34, and CD44 expression compared to the other groups (peri-implant health, peri-implant mucositis)." (PMID 35886240, 2022).
Myelodysplasia (3 papers, 2012 to 2021). Clonal hematopoietic stem cell disorders characterized by dysplasia (ineffective production) in one or more hematopoietic cell lineages, leading to anemia and cytopenia. "Expressions of HSP90 and signalling proteins clients (phosphorylated-AKT (pAKT), Focal Adhesion Kinase (FAK) and phosphorylated-FAK (pFAK)), were assessed in bone marrow mononuclear and CD34-positive (CD34+) cells from 177 patients with myelodysplasia." (PMID 23047954, 2012).
nerve sheath tumors (3 papers, 2015 to 2025). "In addition to morphological differences, the expression pattern of immunohistochemical markers, such as CD34 or EMA, which are positive only for the neurofibromatous component, is useful for differential diagnosis of nerve sheath tumors including HNSTs." (PMID 40255822, 2025).
oral lichen planus (3 papers, 2013 to 2024). Oral lichen planus is a chronic inflammatory oral condition of unknown aetiology characterized by T-cell-mediated chronic immune response and abnormal epithelial keratinization cycle. "Smoking enhanced TLR-2 and CD34 expression in OLP which are considered as inflammatory mediators and are contributing factors in the pathogenesis of oral lichen planus." (PMID 32349717, 2020).
Oral Squamous Cell Carcinoma (3 papers, 2020 to 2025). "In the present study, CD34 expression with histological grading of oral squamous cell carcinoma was significant (p < 0.05) and an insignificant correlation was noted between CD34 expression and tumor vessel invasion (p = 0.23)." (PMID 33383808, 2020). "Therefore, the purpose of our investigation is to evaluate the expression of CD34 and α-SMA in oral squamous cell carcinoma to confirm their diagnostic and prognostic significance and association with tumor differentiation." (PMID 33383808, 2020). "Therefore, further randomized controlled trials with long-term follow-ups correlating and confirming the association of prognostic bio-marker (CD-31, CD34 and α-SMA) expression with behavior and prognosis of oral squamous cell carcinomas are recommended." (PMID 33383808, 2020). "The primary objective was to evaluate and compare the sensitivity and specificity of CD34 immunohistochemistry (IHC) versus conventional hematoxylin and eosin (H&E) staining in detecting lymphovascular emboli (LVE) in oral squamous cell carcinoma (OSCC)." (PMID 41026326, 2025).
osteonecrosis (3 papers, 2019 to 2023). A none disease characterized by death of bone tissue due to a lack of blood supply. "In the CD34+-Exos group, slight osteonecrosis of the trabecular bone was observed." (PMID 31730486, 2019).
Parkinson disease (3 papers, 2017 to 2024). A progressive degenerative disorder of the central nervous system characterized by loss of dopamine producing neurons in the substantia nigra and the presence of Lewy bodies in the substantia nigra and locus coeruleus. "Lastly, in an adult rat model of Parkinson’s disease, CD34+ cells improved limb asymmetry as seen by the cylinder test." (PMID 39075614, 2024). "This study demonstrates for the first time, induction of Parkinson’s disease-like symptoms in female humanized CD34+ mice using MPTP." (PMID 28196514, 2017). "In order to validate that the inflammatory changes in CD34+ humanized mice represented the human disease, human plasma cytokine levels were quantified via ELISA from Parkinson’s disease donors and healthy controls." (PMID 28196514, 2017). "In order to improve understanding of the role of neuroinflammation in Parkinson’s disease, we employed the MPTP injection model using humanized CD34+ mice along with age-matched C57BL/6 mice." (PMID 28196514, 2017). "In addition, analyses of human plasma from Parkinson’s disease donors compared to age-matched, healthy controls demonstrated an increase in a number of pro-inflammatory cytokines in female patients similar to that observed in MPTP-injected female CD34+ mice." (PMID 28196514, 2017).
pilocytic astrocytoma (3 papers, 2018 to 2023). Pilocytic astrocytoma is a rare subtype of low-grade glioma of the central nervous system characterized by a well circumscribed, often cystic, brain tumor with a discrete mural nodule and long, hair-like projections that extend from the neoplastic astrocytes. "Pilocytic astrocytoma was excluded based primarily on the CD34 expression by tumor cells." (PMID 29701169, 2018).
pituitary tumor (3 papers, 2019 to 2025). A benign or malignant neoplasm affecting the pituitary gland. "Compared with normal pituitary tissue, RNA levels of CD31, CD34, and ENG were increased in pituitary tumors by 5.6 (p<0.0001), 22.6 (p<0.0001), and 8.2 (p<0.0001) fold, respectively." (PMID 35600354, 2022). "The RNA transcripts detected in pituitary tumors for CD31, CD34 and ENG were 1.6 x 104, 3.3 x 104, and 1.0 x 105 copies/μg total RNA, respectively." (PMID 35600354, 2022). "Expression of endothelial markers CD31, CD34, and ENG was significantly higher in pituitary tumors, by 5.6, 22.3, and 8.2-fold, respectively, compared to in normal pituitary tissue." (PMID 35600354, 2022). "Because mRNA levels may not truly reflect their respective protein levels, we measured protein levels of CD31, CD34, and ENG in 12 additional pituitary tumors using ELISA assays." (PMID 35600354, 2022).
Pleural effusion (3 papers, 2022 to 2024). The presence of an excessive amount of fluid in the pleural cavity. "SAEs occurred in three (vascular stent occlusion: one, ascites: one, and hepatic encephalopathy: one) and one (hepatic encephalopathy, pleural effusion, and pleurisy) patients in the CD34+ cell and SOC groups, respectively." (PMID 38737403, 2024). "Flow cytometry of pleural effusion showed about 87.8% of myeloid blasts, and their immunophenotypes were positive for CD34, CD117, CD33, and CD56, and partially positive for HLA-DR and CD11b." (PMID 36281103, 2022).
pterygium (3 papers, 2018 to 2021). A wedge-shaped fibrovascular lesion arising from the bulbar conjunctiva and extending to the cornea. "Due to the various postulated etiopathogenesis of pterygium that exists currently, evaluating the effect of intralesional ranibizumab injection on oxidative stress markers in pterygium such as 8-hydroxy-20-deoxyguanosine and on CD34 expression in endothelial cells might be useful." (PMID 35004714, 2021). "Compared with the conjunctiva, several key factors related to angiogenesis, such as PECAM1, CD34, VWF, and ENG, were highly expressed in the pterygium." (PMID 33790949, 2021). "Strong immunoreactivities against progenitor cell markers such as CD34, c-kit, vascular endothelial growth factor (VEGF) receptor 1 and 2 were detected in surgically removed pterygium tissue." (PMID 29653588, 2018). "Additionally, CD34, VWF, and ENG, endothelial cell surface markers, and their positive microvascular counts were markedly higher in pterygium than those in conjunctival tissue." (PMID 33790949, 2021).
pulmonary arterial hypertension (3 papers, 2014 to 2025). Pulmonary arterial hypertension (PAH) is a group of diseases characterized by mean pulmonary artery pressure >20 mmHg and elevated pulmonary arterial resistance leading to right heart failure. "The CD34+ molecule has been described as having greater expression in the endothelium of patients with pulmonary hypertension; in addition, it has also been linked to mast cell migration." (PMID 40722673, 2025).
red cell aplasia (3 papers, 2008 to 2025). "We also successfully transduced human CD34 + HSC derived from a DADA2 patient with pure red cell aplasia and observed restoration of ADA2 expression and enzymatic activity in CD34 + HSC, alongside recovery of stem-cell proliferative and colony forming unit capacity." (PMID 40555830, 2025). "Finally, ALDH+CD34- precursors were not detectable in patients with pure red cell aplasia (PRCA)." (PMID 18510759, 2008).
retinal degeneration (3 papers, 2016 to 2025). Degeneration of the retina. "There are multiple ongoing clinical trials exploring various types of cellular therapies to treat retinal degeneration, but the use of intravitreal injection of CD34+ BMSCs offers several unique advantages." (PMID 39328826, 2025). "Because the rd1 mice typically have a flat ERG signal by 4 weeks of age, the CD34+ cell therapy was administered at an advanced stage of retinal degeneration." (PMID 27537262, 2016). "Nonetheless, this murine model of rapid retinal degeneration revealed some important information about the behavior of human CD34+ cells in eyes with retinal degeneration." (PMID 27537262, 2016). "The purpose of this current study is to further characterize the effect of the human CD34+ cells from BM on the degenerating retina following intravitreal administration using a murine model of hereditary retinal degeneration." (PMID 27537262, 2016). "To date, there are no animal data investigating the effect of intravitreally administered human CD34+ cells from BM in eyes with retinal degeneration." (PMID 27537262, 2016). "In conclusion, this study sheds new light on the behavior of human CD34+ cells following intravitreal injection in murine eyes with retinal degeneration." (PMID 27537262, 2016). "Even though no changes in retinal function could be demonstrated by ERG in these eyes with advanced retinal degeneration, the gene expression changes in the degenerating retina were demonstrated by microarray analysis in eyes treated with CD34+ cells." (PMID 27537262, 2016). "Although a functional benefit of this cell therapy was not seen on ERG in this rapidly progressive retinal degeneration model, molecular changes in the retina associated with CD34+ cell therapy suggest potential trophic regenerative effects that warrant further exploration." (PMID 27537262, 2016). "In Royal College of Surgeons rats with hereditary retinal degeneration, immunosuppressed with cyclosporin to avoid rejection of human cells, the ERG signal was transiently preserved after a single intravitreal injection of human CD34+ BMSCs." (PMID 39328826, 2025). "Additionally, the protective effects of transplanted CD133+CD34+ cells might not be sufficient to attenuate irradiation-induced retinal degeneration for a longer time." (PMID 35223834, 2022).